SOX9 (SRY-box transcription factor 9)
Diseases named in the same sentence as SOX9 in open-access papers (continued):
Sharing a sentence is not in itself a finding about the gene and the disease.
glioblastoma (continued). "Our data confirmed that miR-101 could inhibit proliferation, migration and invasion of human glioblastoma by directly targeting SOX9." (PMID 27911279, 2017). "In light of our findings, the positive correlation between SOX9 expression and CD56 (bright) NK cell infiltration may reflect SOX9’s role in promoting an immunosuppressive environment in glioblastoma, a hypothesis that warrants further mechanistic investigation." (PMID 40692865, 2025). "Furthermore, we showed that temozolomide treatment suppressed SOX10 in glioblastoma model systems, resulting in the enrichment of a slow-cycling SOX9/p27 double-positive cell population, suggesting a role for SOX10-dependent cell-state transitions in therapy-associated tumor progression." (PMID 39285246, 2024). "We found that ARNT2 knockdown not only impaired the cell tumorigenicity in vivo but also resulted in decreased expression of SOX9, POU3F2 and OLIG2, hence placing ARNT2 at the core of transcriptional regulations of glioblastoma cell tumorigenicity." (PMID 29149419, 2018). "Their study demonstrated that miR-145 acted as a tumor-suppressor in glioblastoma since it apparently reduced proliferation, adhesion and invasion of glioblastoma cells, apparently by suppressing the activity of ADD3 and oncogenic protein Sox9." (PMID 28476036, 2017). "For example, in glioblastoma, ARNT2 has been shown to be highly expressed in proliferative subpopulations and to promote tumorigenicity through the regulation of key transcription factors such as SOX9, POU3F2 (BRN2), and OLIG2." (PMID 40723431, 2025). "The FGFR3 signaling pathway, involving genes such as FGFR3, MAPK1/3, and SOX9, is particularly notable because FGFR3–TACC3 fusions are recurrent oncogenic events in IDH-wildtype glioblastomas, driving proliferative and mitogenic signaling through constitutive FGFR3 activation and MAPK/ERK cascades." (PMID 41356219, 2025). "To ascertain the functional relevance of this association, we focused on three transcription factors members of this stem signature SOX9, POU3F2 and OLIG2, since the knockdown of these factors has previously been reported to inhibit glioblastoma cell tumorigenicity in vivo." (PMID 29149419, 2018). "Indeed, we identified that there is an inverse correlation between MKP1 and SOX9 and SOX2 expression in glioblastoma samples." (PMID 29284798, 2017).
liver fibrosis (33 papers, 2012 to 2025). "Among the corresponding transcription factors, GATA6, SOX4, and SOX9 have been reported to be associated with liver fibrosis." (PMID 32442221, 2020). "To investigate the mechanism underlying SOX9 function in liver fibrosis, we explored the consequence of its loss in two well‐established rodent models of the disease." (PMID 29109128, 2017). "In activated HSCs, SOX9 was identified as an upregulated gene linked to liver fibrosis." (PMID 39974732, 2025). "Activating mutations or duplications of the SOX9 locus (a cause of 46,XX disorder of sex development) that might promote liver fibrosis are exceptionally rare and lack the additional context of liver injury." (PMID 29109128, 2017). "However, the association between SOX9 and β-catenin in liver fibrosis still remains largely unknown." (PMID 34531378, 2021). "Indeed, the SOX9 index performed better than other fibrosis risk factors and could potentially assist the stratification of patients with liver fibrosis alongside other measures, such as the cirrhosis risk score." (PMID 29109128, 2017). "Loss of SOX9 in vivo alleviates carbon tetrachloride (CCl4) and bile duct ligated (BDL) induced liver fibrosis, including a reduction in collagen deposition and HSC activation, and improved liver functionality." (PMID 40489560, 2025). "A single Sox9 copy conditionally deleted in Jag1+/− liver tissue reduces cholangiocyte biliary commitment and exacerbates liver fibrosis in Alagille syndrome." (PMID 39974732, 2025). "Felix A. Trogisch and their colleagues found that deletion of endothelial Sox9 inhibited fibrosis and organ dysfunction in 2 mouse models of heart failure and also in models of lung and liver fibrosis." (PMID 39974732, 2025). "In young rats, higher levels of SOX9-positive cells and MSCs activity lead to more severe liver fibrosis." (PMID 39974732, 2025). "And they concluded that reversine inhibited cholestatic DR and liver fibrosis in rats, and decreased bile duct formation through the Dlk1/Notch/SOX9 signaling pathway." (PMID 39974732, 2025). "Athwal et al6 found that SOX9 knockdown reduced hepatic inflammation levels, improved liver function, and inhibited liver fibrosis." (PMID 38993791, 2024). "Similar to NR4A1, SOX9 is also a transcription factor that plays vital roles in sexual differentiation, liver fibrosis and tissue repair." (PMID 36977670, 2023). "Ingenuity pathway analysis (IPA) revealed that the WNT/β-catenin, cardiac hypertrophy, hepatic fibrosis, and pulmonary healing pathways were significantly down-regulated in cells with SOX9 shRNAs, suggesting that SOX9 positively regulates these pathways." (PMID 37491298, 2023). "The expression of both CD24 and SOX9 was identified in our study to strongly correlate with liver fibrosis progression and was specifically elevated in fast-progressor NAFLD patients." (PMID 37296834, 2023). "A previous study showed that lncRNA-NEAT1 sponged miR-139-5p and promoted HSC activation to regulate liver fibrosis by targeting the β-catenin/SOX9/TGFβ1 pathway." (PMID 37919785, 2023). "Expression levels of SOX9 had a particularly strong predictive performance for liver fibrosis progression." (PMID 37296834, 2023). "Consistently, hepatic expression levels of genes, including a progenitor cell marker (Sox9), a liver fibrosis marker (Acta2), and an inflammation marker (Il6), were decreased in Sesn1−/−-BDL vs." (PMID 34880414, 2022). "Inhibition of YAP1 in CCl4 and BDL-induced liver fibrosis by injection of specific YAP1-related inhibitor Verteporfin resulted in decreased expression of SOX9 in HSCs." (PMID 34062960, 2021). "Collectively, our study suggested that miR-139-5p sponged by lncRNA NEAT1 regulated liver fibrosis via targeting β-catenin/SOX9/TGF-β1 Pathway." (PMID 34531378, 2021). "In humans, the expression of SOX9 correlates with the severity of liver fibrosis patients and correlates with the progression to cirrhosis and HCC." (PMID 33182326, 2020).
liver fibrosis (continued). "Inhibition of YAP in CCl4 and BDL mouse models of liver fibrosis by injecting the specific YAP1:TEAD inhibitor verteporfin resulted in reduced SOX9 expression in HSCs." (PMID 31615106, 2019). "The authors reported that increased SOX9 expression correlated with the severity of liver fibrosis in patients with chronic hepatitis C infection." (PMID 31615106, 2019). "The transcription factor Sex determining region Y box 9 (SOX9) is actively involved in scar formation and its prevalence in patients with liver fibrosis predicts progression." (PMID 30559459, 2018). "SOX9 outperformed all other current measures predicting outcome in liver fibrosis and would allow novel patient stratification for care and treatment." (PMID 29109128, 2017). "Next, we explored the effect of eliminating SOX9 expression on chronic inflammation in liver fibrosis." (PMID 29109128, 2017). "Taken together, our data support a model whereby injury induces SOX9 downstream of YAP1 in HSCs to promote liver fibrosis." (PMID 29109128, 2017). "Our data support a critical role for SOX9 in liver myofibroblasts to promote liver fibrosis and open up the potential for SOX9 and its dependent pathways as biomarkers or antifibrotic targets for improving liver scarring." (PMID 29109128, 2017). "The HSC/Hep SOX9 index was progressively higher for those patients whose liver fibrosis worsened over the subsequent 3 years." (PMID 29109128, 2017). "SOX9 protein and mRNA were detected in αSMA‐positive spindle‐shaped cells in sections of liver fibrosis induced by CCl4 and BDL as previously." (PMID 29109128, 2017). "Understanding the role and regulation of SOX9 during liver fibrosis will provide insight into its potential modulation as an antifibrotic therapy or as a means of identifying potential ECM targets, similar to OPN, as biomarkers of fibrosis." (PMID 22488688, 2012). "Here, in rat and mouse models of liver fibrosis, nuclear Sox9 localized to desmin-positive cells, confirming its presence in HSCs." (PMID 22488688, 2012). "The onset of OPN production during rHSC activation, its reduction in activated HSCs after Sox9 abrogation, and the binding of SOX9 to an upstream OPN enhancer element infers that the transcription factor is required for OPN expression during liver fibrosis." (PMID 22488688, 2012). "They noted that SOX9, a crucial transcriptional mediator in the signaling pathway, might enhance Spp1 expression during liver fibrosis progression." (PMID 39974732, 2025). "SOX9, is a transcription factor that plays a specific role in liver fibrosis." (PMID 40421024, 2025). "The SOX9 gene locus is not only extensive but also intricate, and it could promote fibrosis in different organs or tissues, including cardiac fibrosis, liver fibrosis, kidney fibrosis, pulmonary fibrosis, as well as other organ fibrosis." (PMID 39974732, 2025). "Additionally, the expression of GITRL, a cytokine, is notably elevated in SOX9-positive hepatic progenitor cells, which are important in liver fibrosis." (PMID 39974732, 2025). "Furthermore, the overexpression of SOX9 significantly alleviated the effects of LDHA silencing on activated HSCs, suggesting that SOX9 operates downstream of H3K18 lactylation in the promotion of liver fibrosis." (PMID 39974732, 2025). "In addition, deletion of TFE3 in F3KO led to a reduction in liver fibrosis, a decrease in SOX9 expression in hepatocytes, and normalization of mTORC1 activity, as demonstrated by P-S6 immunostaining and immunoblot for P-4EBP1." (PMID 40189703, 2025). "Accumulating studies have confirmed that SOX9 could regulate collagen production, contributing to liver fibrosis, renal fibrosis, and cardiac fibrosis." (PMID 35586685, 2022). "Our study indicated that β-catenin bound with SOX9 to promote HSCs activation and liver fibrosis." (PMID 34531378, 2021).
liver fibrosis (continued). "Herein, our study verified that lncRNA NEAT1 could target and suppress the expression of miR-139-5p directly to promote HSCs activation and excerabate liver fibrosis via β-catenin/SOX9/TGF-β1 axis." (PMID 34531378, 2021). "In the liver, the deletion of SOX9 in vivo has been shown to attenuate CCL4-induced liver fibrosis." (PMID 34520400, 2021). "Moreover, the DR of Sox9+ cells, liver fibrosis and infiltration of NKp46+ cells was significantly reduced in the absence of Opn." (PMID 30778201, 2019). "Our data open up the potential for SOX9 and its dependent pathways as biomarkers or as targets for lessening liver scarring, improving hepatic chronic inflammation and halting the progression of liver fibrosis toward cirrhosis." (PMID 29109128, 2017). "Here, we studied the requirement for SOX9 in vivo in liver fibrosis." (PMID 29109128, 2017). "Interestingly, Avagacestat significantly inhibited SOX9 expression suggesting Notch regulates SOX9 expression and collagen-I expression in liver fibrosis." (PMID 26658360, 2015). "Taken together these data support a model of inter-dependent states of high and low EPIM and SOX9 in determining whether ECM is deposited or degraded in liver fibrosis." (PMID 24971829, 2014). "Further understanding of EPIM's role may lead to opportunities to modulate SOX9 as a therapeutic avenue for liver fibrosis." (PMID 24971829, 2014). "SOX9 was responsive to Hh signaling in our models of liver fibrosis." (PMID 22488688, 2012). "Previously, we have demonstrated that Sex-determining region Y-box 9 (SOX9) is ectopically expressed during activation of hepatic stellate cells (HSC) when it is responsible for the production of type 1 collagen, which causes scar formation in liver fibrosis." (PMID 22488688, 2012). "Additionally, the higher expression level of SOX9 was found in hepatic fibrosis in mice." (PMID 39974732, 2025). "The mRNA levels of liver fibrosis markers (Acta2, Col1a1, Col3a1, and Timp1), cholangiocyte proliferation markers (Krt7 and Krt19), inflammation markers (Il6 and Il1b), and the progenitor cell marker (Sox9) were markedly decreased in miR-200c-BDL mice compared to con-BDL mice." (PMID 34880414, 2022). "A study has indicated that SOX9 could promote HSCs activation and exacerbate liver fibrosis." (PMID 34531378, 2021). "However, the interplay between SOX9 amd β-Catenin in liver fibrosis remains poorly known." (PMID 34531378, 2021). "In contrast, aged mice exhibited hepatic fibrosis, with increased collagen deposition and upregulation of genes related to fibrosis (Acta2, MMP2, TGF-ß1, and Col1a2), cirrhosis (CXCR4, SOX9, DCN, and MFAP4), and cancer (Bcl2, CDKN2a, c-Myc, and Fn1)." (PMID 39851554, 2025). "It was found that knockdown of LDHA reduced H3K18 lactylation levels by decreasing SOX9 transcription, which in turn diminished HSC activation and extracellular matrix deposition, and alleviated liver fibrosis in rats." (PMID 40421024, 2025). "Indeed, infected SOX9-/- mice display a higher proportion of Ly6clo monocytes, where these populations have previously demonstrated restorative functions in inflammatory liver conditions, including rotavirus mediated liver inflammation and chronic CCl4-induced liver fibrosis." (PMID 40489560, 2025). "When the liver injury occurs, Sox9 may act on hepatocyte extracellular matrix genes, leading to extracellular matrix deposition 78, 79 and induction of non-coding RNA H19 by binding to the conserved promoter region of the H19 gene, while participating in hepatocyte apoptosis and liver fibrosis." (PMID 38993564, 2024). "In clinical samples of liver fibrosis, CD24+CK19+/CD24+SOX9+ ductular reactive cells were abundantly found in regions of ductular reaction, suggesting the activation and expansion of ductular reactive cells." (PMID 37784089, 2023).
liver fibrosis (continued). "SOX9, an important regulator of ECM genes, plays a vital role in the pathological mechanisms of various diseases, such as liver fibrosis, glomerular sclerosis, and heart valve calcification." (PMID 35586685, 2022). "After BDL in rats, Notch receptor activation, combined with overexpression of SOX9, enhanced BEC proliferation and induced hyper-hepatic fibrosis." (PMID 34062960, 2021). "In this study, we found that β-catenin bound with SOX9 and promoted TGF-β1 transcription to activate HSCs and induce liver fibrosis according to bioinformatic analysis." (PMID 34531378, 2021). "Herein, we uncovered a new NEAT1/miR-139-5p axis promoting HSCs activation and driving liver fibrosis development by modulating the β-catenin/SOX9/TGF-β1 signaling, providing potential targets for the early diagnosis and treatment of liver fibrosis." (PMID 34531378, 2021). "In CCl4 or DEN/CCl4-induced liver fibrosis, co-immunofluorescene of YFP with ductal BECs markers (CK19, SOX9, OPN) demonstrated ductal metaplasia of hepatocytes into ductal BECs was diminished in DAPT-treated mice." (PMID 32251270, 2020). "Furthermore, we examined the relative mRNA expression levels of key markers related to hepatic fibrosis (Acta2, Cola2, TGF-β1, and MMP2), cirrhosis (CXCR4, SOX9, DCN, and MFAP4), and cancer (Bcl2, CDKN2a, c-Myc, and Fn1) across the experimental groups." (PMID 39851554, 2025). "Additionally, the SOX9/INHBB axis mediates the activation of HSCs, which produce collagen and the extracellular matrix, inducing liver fibrosis." (PMID 39974732, 2025). "There was no impact from eliminating SOX9 in hepatocytes and cholangiocytes [which furthers the argument against epithelial‐to‐mesenchymal transition as a significant mechanism for liver fibrosis]." (PMID 29109128, 2017). "Direct in vivo evidence for SOX9 function in liver fibrosis (rather than regeneration) has been lacking." (PMID 29109128, 2017).
ovarian carcinoma (31 papers, 2012 to 2025). A malignant neoplasm originating from the surface ovarian epithelium. "The aberrant expression of SOX9 has also been associated with cisplatin (CDDP) resistance in ovarian cancer cells." (PMID 40240356, 2025). "We propose an underlying mechanism of cytoplasmic SOX9-mediated suppression of cancer stem cell death, subsequently resulting in ovarian cancer survival in HGOC." (PMID 35159173, 2022). "Furthermore, SOX9 has been recently identified as maintaining chemoresistance in ovarian cancer cells through altered accessibility at its associated enhancer, was among the genes near a CORE which was gained in the resistant PEO4 line." (PMID 34090482, 2021). "SOX9 is also overexpressed in ovarian cancer and it could be a possible diagnostic marker of ovarian carcinomas." (PMID 26384302, 2015). "The findings from the colony formation assay corroborated that SOX9 fosters resistance to olaparib in ovarian cancer cells." (PMID 40240356, 2025). "In conclusion, these findings suggested that USP28 plays a role in maintaining the stability of SOX9 in ovarian cancer." (PMID 40240356, 2025). "Overexpression of SOX9 augmented the resistance of ovarian cancer cells to olaparib, while knockdown of SOX9 exerted an opposing effect." (PMID 40240356, 2025). "In conclusion, targeted inhibition of USP28 promoted ubiquitination-mediated degradation of SOX9, thereby impairing DNA damage repair capabilities and sensitizing ovarian cancer cells to PARPi." (PMID 40240356, 2025). "Here, we elucidated that the upregulation of SOX9 renders ovarian cancer resistant to olaparib in vitro and in vivo." (PMID 40240356, 2025). "In the current study, we report for the first time that SOX9 is positively correlated with PARPi resistance in ovarian cancer." (PMID 40240356, 2025). "Experimental validation has unequivocally verified the effectiveness of targeting SOX9 as a potent therapeutic strategy in numerous malignancies, including ovarian cancer." (PMID 40240356, 2025). "Our study demonstrated that elevated expression of SRY-box 9 (SOX9) contributes to olaparib resistance in ovarian cancer." (PMID 40240356, 2025). "The MTT assay showed that SOX9 knockdown sensitizes ovarian cancer cells to olaparib, whereas SOX9 overexpression led to resistance to olaparib treatment." (PMID 40240356, 2025). "SOX9 is notably upregulated in ovarian cancer tissues, and its high expression is indicative of poor prognosis, lymph node metastasis, and chemotherapy resistance." (PMID 40240356, 2025). "Our further research showed that USP28/SOX9 modulate the HRR activity of ovarian cancer by regulating SMARCA4, UIMC1, and SLX4 expression." (PMID 40240356, 2025). "In conclusion, our study showed that USP28 directly interacts with SOX9 to decrease its ubiquitination and degradation, which subsequently enhances the DNA damage repair and contributes to PARPi resistance in ovarian cancer cells." (PMID 40240356, 2025). "For example, there is a significant association between Sox9 and the stemness-regulating enzyme ALDH1A1, which is primarily located in the cytoplasm of high-grade ovarian carcinoma with lymph node metastasis." (PMID 38978960, 2024). "Previous findings also find that the expression of SOX9 in OC tissues was upregulated which play an important role in regulates the chemoresistance of ovarian cancer cell to cisplatin-based chemotherapy." (PMID 37468993, 2023). "While SOX10’s involvement in ovarian carcinomas was assessed, other common expression markers studied for ovarian cancer include SOX8 and, notably, SOX9, which has been implicated in various signaling pathways in ovarian cancer development." (PMID 38132479, 2023). "Further experiments are required to explore the therapeutic effect of SOX9 silencing and to examine its side effects in ovarian cancer." (PMID 35159173, 2022).